MDS2 (myelodysplastic syndrome 2 translocation associated)
Gene: Long non-coding RNA gene on chromosome 1 (23,581,495 to 23,640,574, forward strand). Ensembl gene ENSG00000197880.
Diseases named in the same sentence as MDS2 in open-access papers:
MDS2 is named in the same sentence as 9 diseases in open-access papers, as found by Europe PMC text mining. Sharing a sentence is not in itself a finding about the gene and the disease. The quoted sentences say what the papers report.
appendix cancer (1 paper, 2022). "On average, MDS2 mutations are found in 0.09% of all cancers; the most common types are breast cancer, appendix cancer, lung cancer, and colon cancer." (PMID 36251702, 2022).
myelodysplastic syndrome (1 paper, 2022). A clonal hematopoietic disorder characterized by dysplasia and ineffective hematopoiesis in one or more of the hematopoietic cell lines. "The MDS2 is a gene that encodes a protein that functions in the onset of myelodysplastic syndrome (MDS)." (PMID 36251702, 2022).
ovarian carcinoma (1 paper, 2022). A malignant neoplasm originating from the surface ovarian epithelium. "Multiple mutations in MDS2 have been shown in breast and ovarian cancer." (PMID 36251702, 2022).
MDS2 also shares sentences with these, for which no sentence is quoted: breast carcinoma (1 paper); cancer (1); colon cancer (1); lung carcinoma (1); Myelodysplasia (1); testicular germ cell tumour (1).